BAX (BCL2 associated X, apoptosis regulator)
Diseases named in the same sentence as BAX in open-access papers (continued):
Sharing a sentence is not in itself a finding about the gene and the disease.
cancer (continued). "In summary, despite its limitations, this meta-analysis suggests BAX SNPs and susceptibility lack obvious connection while it leads to worse OS in cancer populations." (PMID 30024563, 2018). "We show here that MET inhibition in HSP27‐silenced cells was also associated with the increase in BAK and BAX proteins, whose increased levels have been correlated with better responses of cancer cells to chemotherapy." (PMID 28182330, 2017). "Mutation of the BAX gene is widely observed in genetically unstable cancers of the colorectum, stomach, and endometrium." (PMID 28556798, 2017). "Because of the potential failure of DNA repair machinery, the cancer cells are forced to enter the process of apoptotic cell death as shown by the increasing expression of BAX, which has been reported in other studies." (PMID 26309132, 2015). "TOB1 antagonizes the v-akt murine thymoma viral oncogene (AKT) signaling and induces cancer cell apoptosis by activating BCL2-associated X (BAX) protein and inhibiting the BCL-2 and BCL-XL expressions." (PMID 26694352, 2015). "In a further study of the possible mechanism underlying plasma-induced cancer cell apoptosis at 24 h, we determined the mRNA gene expressions of Bcl-2, BAX, BAK1 and H2AX by real time quantitative PCR analysis." (PMID 25715710, 2015). "Then, we divided the cancer cell lines into two subgroups: BAX pocket mutated (BAX-Pmut) and BAX wild-type (BAX-WT) using the BAX protein pocket somatic mutation profiles." (PMID 25360158, 2014). "The BAX gene had the highest number of cancer cell line mutations in the pocket regions (PDB ID: 1F16)." (PMID 25360158, 2014). "We divided the cancer cell lines into two subgroups: BAX gene mutated (BAX-mut) and BAX gene wild-type (BAX-WT), using all of BAX gene’s somatic mutation profiles." (PMID 25360158, 2014). "Furthermore, cancer cells harboring biallelic mutations in the apoptotic effector BAX are completely refractory to ABT-263/navitoclax, independent of DDR induction by TIS agents." (PMID 40055336, 2025). "It seems that BAX may become a very important risk of development marker in diseases, including cancers." (PMID 41614769, 2025). "Therefore, an unprimed, incompetent state does not accurately reflect a pan-refractory response to BH3 senolytics in BAX-deficient TIS cancer cells." (PMID 40055336, 2025). "One such SNP, characterized by the substitution of guanine for adenine at position 248 (rs4645878) of the promoter region of the BAX gene, may be associated with several diseases, including various types of cancer." (PMID 41614769, 2025). "Research suggests that polymorphisms/mutations in the BAX gene may be associated with changes in mRNA and protein expression, which may translate into an increased risk of developing diseases, including cancer." (PMID 41614769, 2025).
cancer (continued). "For example, in humans, the decline in BCL2 expression and the alteration of the BCL2/BAX ratio with age has been associated with a decrease in tissue repair capacity and an increased incidence of age-related diseases such as cancer, cardiovascular disease, and neurodegenerative disorders." (PMID 40646808, 2025). "This suggests that, although TIS deepening correlates with increased BCL-xL dependence, the requirement for mitochondrial priming varies as even minimally primed TIS cells (including BAX-deficient TIS cancer cells) can still be eliminated by BCL-xL-targeted senolytics." (PMID 41280927, 2025). "The results showed that there were many types of cancer whose area under the curve (AUC) value of BAX diagnostic was greater than 0.9, among which GBM was 0.993, TGCT was 0.981, CESC was 0.979, LGG was 0.975, ESCA was 0.942, LIHC was 0.930, THCA was 0.926 and READ was 0.903." (PMID 39074253, 2024). "BAX activation causes the permeabilization of the mitochondrial membrane, which results in the release of the apoptotic component Cytochrome c and the death of the cancer cells." (PMID 38554983, 2024). "Moreover, we detected the expression of CCDC113, MMP2 (associated with migration and invasion of cancer cells), BAX and BCL2 in CCDC113 overexpression cells and control cells." (PMID 39261464, 2024). "Next, we evaluated the mutation status of BAX in various cancer types." (PMID 39074253, 2024). "Our group recently demonstrated that the interaction of BCL2 and BAX through their TMDs contributes to the modulation of cell death; therefore, phenotyping mutations affecting these TMDs could have relevance for cancer cell survival." (PMID 38670940, 2024). "Further research is needed to clarify whether BAX alterations constitute a cancer risk factor, particularly in UM-enriched patient or family populations." (PMID 38892746, 2024). "Finally, BAX is a critical effector of mitochondrial apoptosis linked to apoptosis-resistant cancer cells." (PMID 37999208, 2023). "Conversely, BAX −248G>A is a polymorphism associated with several cancers." (PMID 38003498, 2023). "Finally, avoidance of apoptosis is a typical characteristic of cancer, including BC; therefore, BCL2-associated X-protein (BAX) and caspase-8 (CASP8), which participate in intrinsic and extrinsic apoptotic pathways, merited further investigation." (PMID 37264344, 2023). "In summary, MOAP1 plays a critical role in the development and progression of cancers and neurological diseases by regulating a few genes related to cellular apoptosis such as BAX and RASSF1A and interacting with disease-associated miRNAs, including miR-25 and miR1228." (PMID 35269511, 2022). "From the point of view of the cancer cell, the loss of BAX/BAK may be desirable for avoiding apoptosis but disastrous for preventing senescence induced by ploidy changes and perhaps other yet-to-be elucidated stressors." (PMID 34725331, 2021). "Indeed, anti-HER3 antibody-induced apoptosis in DU145 cells was lower than in the other tested cancer cell lines, probably because BAX deficiency prevented BIM-mediated apoptosis." (PMID 31443721, 2019). "The BCL-2 family of proteins, including anti-apoptotic BCL-2 and pro-apoptotic BAX, are critical regulators of the mitochondrial apoptotic pathway and they have been associated with a more aggressive treatment and drug resistance in cancer chemotherapy." (PMID 30754694, 2019). "Existing studies have debated whether the BAX gene polymorphism increased cancer susceptibility and suggested adverse outcomes." (PMID 30024563, 2018).
cancer (continued). "Although considerable efforts were made to detect the possible association between BAX SNPs and cancer susceptibility and prognosis, caution must be dealt with in the interpretation of these findings because of the large heterogeneity or small sample size design in our study." (PMID 30024563, 2018). "The association between BAX gene polymorphisms and cancer susceptibility has been reported." (PMID 30024563, 2018). "Our study updated the data on BAX polymorphism and the risk of cancer." (PMID 30024563, 2018). "Meta-analysis BAX rs4645878 polymorphism and cancer risk (G vs A)." (PMID 30024563, 2018). "Summary odds ratios (ORs) and hazard ratios (HRs) with their 95% confidence intervals (CIs) were harnessed to determine the strength of correlation between BAX polymorphisms and cancer susceptibility and prognosis, which were combined using fixed- or random-effects models as appropriate." (PMID 30024563, 2018). "Besides, our results corroborating BAX polymorphism effected on cancer prognosis for the first time." (PMID 30024563, 2018). "It is known that high expression of BAX is associated with improved chemotherapy responsiveness whereas PGRMC1 has a negative impact on chemotherapy by promoting the survival of treated cancer cells." (PMID 24628760, 2014). "Lower levels of BAX are associated with a worse prognosis for some types of cancer." (PMID 16103918, 2005). "Furthermore, BAX may participate in proliferation and metastasis of many cancers and was associated with methylation." (PMID 39074253, 2024). "Therefore, cancer cell lines deficient in both BAX and BAK may serve as ideal models for examining the drug resistance mechanisms." (PMID 31551763, 2019). "Similarly, loss of pro-apoptotic proteins such as BAX or BAK is frequently observed in cancers." (PMID 29156771, 2017). "In F9 cancer cells, incubation with recombinant SELENOV was associated with significantly increased mRNA levels of several pro-apoptotic genes (BAX, PUMA, CASP-3) and decreased mRNA levels of two anti-apoptotic BCL-2 family genes (BCL-xL and BCL-2)." (PMID 41463386, 2025). "Brentuximab’s significant effect on apoptotic markers, like Caspase-3 and BAX, across multiple cell lines further confirms its role in inducing cell death through intrinsic apoptotic pathways, especially in aggressive cancers like MDA-MB-231 and U-937." (PMID 39805861, 2025). "Specifically, PACS1 has been implicated in apoptosis through its regulation of BAX and BAK, highlighting its potential impact on cancer cell survival and treatment responses." (PMID 40728977, 2025). "Gene expression analysis revealed upregulation of pro-apoptotic genes (BAX, Caspase 3, and Caspase 9) in cancer cells, alongside a decrease in anti-apoptotic BCL-2 expression." (PMID 39805861, 2025). "This explains the altered response of TIS cancer cells to the HRK peptide and their susceptibility to ABT-263/A1331852, which restores apoptotic competence by disrupting the BCL-xL/BAX interaction." (PMID 41280927, 2025). "Apoptosis-mediated death of cancer cells is achieved by the upregulation of pro-apoptotic genes, such as BAX, BID, and BAK, and the downregulation of anti-apoptotic genes, such as BCL-2 and BCL-XL respectively." (PMID 40756996, 2025).
cancer (continued). "The BAX/BCL2 ratio, which determines the susceptibility of cells to apoptosis, can affect cancer cell behavior, and its high levels lead cells to apoptosis." (PMID 40498096, 2025). "Its anticancer mechanisms involve inducing apoptosis and autophagy in cancer cells, upregulating pro-apoptotic genes like BAX, and activating caspase pathways." (PMID 40805798, 2025). "Genetic ablation of the apoptotic effectors BAX and BAK in cancer cells results in the loss of MOMP." (PMID 41280927, 2025). "The quantity of pro-apoptotic markers, such as cleaved caspase-3 (CASP3) and Bcl2-associated X protein (BAX), is increased in POFUT1-silenced cancer cells, while anti-apoptotic proteins like BCL2 decreased." (PMID 40773107, 2025). "Up-regulation of BAX expression has been shown to impair radiation-induced apoptosis, leading to enhanced survival of cancer cells after radiotherapy." (PMID 40652278, 2025). "One study demonstrated that Celastrus orbiculatus extract (COE) upregulates the expression of pro‐apoptotic proteins BAX and Cleaved‐Caspase‐3 while downregulating anti‐apoptotic proteins Bcl‐2 and Bcl‐xL in cancer cells." (PMID 41231037, 2025). "It is worth noting that BAX gene showed high expression specific to tumor cells and showed obvious spatial localization characteristics in cancer nests, and the proportion of malignant cells with high expression of BAX in ccRCC samples significantly increased." (PMID 40382614, 2025). "This protein duo is also involved in ICD, as BAX/BAK activation is essential for CALR exposure during cancer death by chemical and physical means." (PMID 41304887, 2025). "Polyphenols such as epigallocatechin-3-gallate have been found to inhibit cancer cell proliferation and regulate key apoptosis-related proteins (e.g., Bid, BAX, and Bcl-2), thereby promoting cancer cell death." (PMID 40871098, 2025). "Because of the protein’s prominent role in regulating apoptosis, differences among BAX isoforms are especially interesting in the context of cancers." (PMID 40963109, 2025). "It was found that apoptosis was induced in cancer cells by increasing BAX levels and decreasing Bcl‐2 levels; CYCS and CASP3 levels, which are ROS‐assisted apoptotic markers, also increased." (PMID 40318008, 2025). "GTs tend to reduce the ΔΨm of cancer cells concomitantly with an increase in the bcl-2-like protein 4 (BAX) and Bcl-2 homologous antagonist/killer (BAK) proteins, which are key molecular drivers of MOMP." (PMID 41304887, 2025). "We document the usefulness of this feature by comparing PLIP interactions of the cancer drug venetoclax with the native protein–protein interaction of Bcl-2 and BAX." (PMID 40347107, 2025). "On the other hand, vinorelbine is an anti-microtubule agent that triggers apoptosis in cancer cells by reducing the formation of heterodimers between Bcl2 and the pro-apoptotic gene BAX." (PMID 37622179, 2024). "We further investigated the expression differences of BAX protein in multifarious cancer types, and BAX expression was significantly elevated in many tissues, including GBM, LIHC, LUAD and COAD." (PMID 39074253, 2024). "The results indicate that LP treatment can increase the pro-apoptotic BAX protein level, while decreasing the anti-apoptotic Bcl-2 protein level in all cancer cell lines." (PMID 38258008, 2024). "Immunofluorescence analysis corroborated these findings, demonstrating a significantly increase in BAX fluorescence intensity in cancer cells treated with anlotinib alone or in combination with DDP, while the fluorescence intensity of BCL2 was decreased." (PMID 39508048, 2024).
cancer (continued). "Immune checkpoint therapy has shown considerable promise in treatment of cancers currently, many immune checkpoints are highly positively correlated with BAX, such as ENTPD1, CD80, and CD28." (PMID 39074253, 2024). "Subsequently, we found the potential relationship between BAX gene alteration and clinical survival in diverse cancer types." (PMID 39074253, 2024). "PQBP1 promotes BAX exon 2 skipping to generate a truncated isoform that undergoes degradation by nonsense‐mediated mRNA decay, thus making cancer cells resistant to apoptosis." (PMID 38342602, 2024). "The results of qRT-PCR showed that the treatment of cancer cells with L. buchneri MVs led to a remarkable enhancement in the expression of BAX, CASP3, and CASP9 genes." (PMID 38326490, 2024). "Glabridin promotes tumor cell apoptosis by upregulating BAX, Caspase-3, Caspase-8, and Caspase-9 and downregulating Bcl-2, and inhibits cancer cell invasion and metastasis by downregulating N-Cadherin and upregulating E-Cadherin to reduce cell adhesion." (PMID 39723390, 2024). "The box plot showed that BAX expression was notably correlated with different tumor stages in these cancers (P < 0.05)." (PMID 39074253, 2024). "CLU plays a crucial role in providing chemoresistance by sequestering BAX to prevent BAX-mediated apoptosis in cancer cells." (PMID 38447939, 2024). "To reveal the role of BAX in the pan-cancer immune microenvironment, we evaluated the correlation between BAX expression and six types of immune cells by TISIDB, aided by six other algorithms." (PMID 39074253, 2024). "Mutants altering the BCL2 TMD hetero-interactions with pro-apoptotic BAX remain particularly interesting due to the possible impacts on cancer cell survival and therapeutic resistance." (PMID 38670940, 2024). "Accumulating studies have indicated that the induction of BAX-regulated apoptosis has become a pivotal strategy for drug resistance and cancer treatment." (PMID 39074253, 2024). "And BAX participates in a critical step of the mitochondria-dependent apoptosis, which is frequently dysregulated in cancers." (PMID 39074253, 2024). "The high doses of Mocetinostat drug significantly induce apoptosis and suppress cancer cell proliferation through increased pro-apoptotic proteins (BAX) and a down level of anti-apoptotic proteins(Bid, Bcl2)." (PMID 38645087, 2024). "Remarkably, BAX/BCL–2 ratio has been widely accepted as a protein expression pattern to estimate the eventual outcome of apoptosis expression in cancer patients." (PMID 38499634, 2024). "When the body contains elevated levels of anti-apoptotic proteins such as B cell lymphoma-2 (Bcl-2) and decreased levels of pro-apoptotic proteins like Bcl2-associated X protein (BAX), cancer cells exhibit anti-apoptotic activity, and malignancy increases." (PMID 38915462, 2024). "We observed that BAX expression was positively correlated with the degree of immune infiltration in a variety of cancers." (PMID 39074253, 2024).